CD55 (CD55 molecule (Cromer blood group))
Diseases named in the same sentence as CD55 in open-access papers (continued):
Sharing a sentence is not in itself a finding about the gene and the disease.
bullous pemphigoid (1 paper, 2018). Bullous pemphigoid (BP) is the most common form of autoimmune bullous dermatosis. "Our data show for the first time that compromised complement inhibition due to diminished CD55 levels may be implicated in the pathogenesis of bullous pemphigoid." (PMID 30473747, 2018). "We therefore hypothesized that loss of CD55, a typical complement regulator acting via suppression of C3 and C5 activity, contributes to bullous pemphigoid development." (PMID 30473747, 2018). "Moreover, complement activation was blocked by exogenous recombinant CD55 protein in both skin sections and keratinocytes exposed to pathogenic antibodies from patients with bullous pemphigoid." (PMID 30473747, 2018). "Thus, CD55 deficiency is a crucial factor in bullous pemphigoid pathogenesis, suggesting that increasing CD55 levels may exert a therapeutic effect." (PMID 30473747, 2018). "To further investigate the regulatory role of CD55 in bullous pemphigoid pathogenesis, we next exposed frozen skin sections from healthy volunteers and HaCaT cells to pathogenic IgG and fresh serum from healthy controls containing complement components." (PMID 30473747, 2018). "In contrast, we observed only weak staining of CD55 in epidermal specimens from patients with bullous pemphigoid, consistent with the results of our western blot analysis." (PMID 30473747, 2018). "We found that CD55 levels were significantly lower in the lesions of patients with bullous pemphigoid (n = 8) compared to those in skin samples from healthy controls (n = 6)." (PMID 30473747, 2018). "Here, we investigated the involvement of CD55 in bullous pemphigoid, as little is known regarding its role in this disease." (PMID 30473747, 2018). "qRT-PCR and Western blotting revealed that CD55 was downregulated in skin specimens from three patients with bullous pemphigoid in comparison to those from two healthy controls." (PMID 30473747, 2018). "Notably, a significant increase in the expression of TNF-α and IFN-γ, administration of which downregulated CD55 levels in HaCaT cells, was observed in the sera of patients with bullous pemphigoid (n = 38) compared to that in healthy controls (n = 19)." (PMID 30473747, 2018). "Together, these results indicate that CD55 expression is abnormally downregulated in the epidermis of patients with bullous pemphigoid, and this may be responsible for the activation of the complement system and C3b deposition in the DEJ of BP patients." (PMID 30473747, 2018). "Here, we observed CD55 downregulation in the lesional skin of patients with bullous pemphigoid." (PMID 30473747, 2018). "In addition, we examined CD55 expression in peripheral blood cells from patients with bullous pemphigoid by flow cytometry." (PMID 30473747, 2018). "In addition, elevated TNF-α and IFN-γ levels in patients with bullous pemphigoid downregulated CD55 via activation of ERK1/2 signaling." (PMID 30473747, 2018). "Our results demonstrate a role for CD55 in bullous pemphigoid progression and suggest that it may serve as a therapeutic target for this disease." (PMID 30473747, 2018). "To test this hypothesis, we assessed CD55 expression in the lesions of bullous pemphigoid patients and examined the mechanism in vitro." (PMID 30473747, 2018). "Here, we found that recombinant CD55 can inhibit C3b deposition in autoantibody-mediated complement activation, suggesting that complement-based therapies should be considered for the treatment of bullous pemphigoid." (PMID 30473747, 2018). "On the basis of the present results, it may be concluded that CD55 protein levels are significantly downregulated in the lesional skin of patients with bullous pemphigoid." (PMID 30473747, 2018). "Our results demonstrated that CD55 was downregulated by TNF-α and IFN-γ via the ERK1/2 pathway, clarifying the involvement of abnormal complement activation in bullous pemphigoid pathogenesis." (PMID 30473747, 2018).
bullous pemphigoid (continued). "Taken together, these results suggest that lack of CD55 leads to complement activation in the pathogenesis of bullous pemphigoid." (PMID 30473747, 2018).
chronic lymphocytic leukemia (1 paper, 2021). "Moreover, in a clinical study of chronic lymphocytic leukemia (CLL), the expression of CD59 but not CD55 significantly increased in patients who failed to clear CLL cells from circulation after rituximab treatment." (PMID 34956875, 2021).
co-infection (1 paper, 2025). "In parallel, ADGRE5-ALCAM-related co-stimulatory and adhesion interactions showed pair-specific dynamics: CD6-ALCAM and ITGAV-ITGB1-ADGRE5 were most prominent in the HIV-mono group and diminished with Mtb co-infection, whereas CD55-ADGRE5 did not display a comparable monotonic trend." (PMID 41394852, 2025).
colorectal tumours (1 paper, 2001). "Immunohistochemical staining of colorectal tumours also revealed high expression of CD55 in the stroma." (PMID 11139317, 2001).
common variable immunodeficiency (1 paper, 2022). "Immunological enteropathies, all rare, include graft-versus-host disease (GVHD), common variable immunodeficiency (CVID), CD55 deficiency, transplantation rejection enteropathy, and autoimmune enteropathy." (PMID 35372420, 2022).
demyelination (1 paper, 2023). "However, only CD59-deficient patients, and not CD55-deficient patients, are under frequent PNS attack leading to recurrent PNS demyelination episodes and conduction block, indicating the crucial role of CD59 in protecting myelin from complement attack." (PMID 37875972, 2023).
developmental delay (1 paper, 2018). "Furthermore, the cell surface levels of CD55 and CD59 were on average lower in cells that were derived from individuals with mutations in PGAP3 compared to individuals with mutations in PIGV, although this did not correspond to a higher prevalence of seizures or a more severe developmental delay." (PMID 29310717, 2018).
endometriosis (1 paper, 2024). The growth of functional endometrial tissue in anatomic sites outside the uterine body. "In patients with endometriosis, CD55 and other highly expressed cytoprotective proteins guard damaged cells against complement-mediated cytolysis during stress." (PMID 38660311, 2024).
enterovirus infection (1 paper, 2025). "In addition to supporting the biogenesis of CD55, which is a GPI anchor protein and an entry factor for some echoviruses, the GPI anchor synthesis machinery also supports several other enterovirus infections by enhancing viral replication and replication organelle biogenesis." (PMID 41252368, 2025). "However, we hypothesized that PIG genes support enterovirus infection not solely through CD55 production, because EV71 and CVB5, both of which could infect CD55-deficient cells, also require PIG genes for efficient infection." (PMID 41252368, 2025).
esophageal adenocarcinoma (1 paper, 2019). A malignant tumor with glandular differentiation arising predominantly from Barrett mucosa in the lower third of the esophagus. "Overexpression of CD55 in Barrett's esophagus has also been associated with esophageal adenocarcinoma risk." (PMID 31164885, 2019).
Familial hemophagocytic lymphohistiocytosis (1 paper, 2024). Familial Hemophagocytic lymphohistiocytosis (FHL) is a rare primary immunodeficiency characterized by a macrophage activation syndrome (see this term) with an onset usually occurring within a few months or less common several years after birth. "It provided direct diagnostic insights for IEIs such as severe combined immunodeficiency, Omenn syndrome, MHC class II deficiency, familial hemophagocytic lymphohistiocytosis, and CD55 deficiency." (PMID 39072316, 2024).
follicular lymphoma (1 paper, 2007). Follicular lymphoma is a form of non-Hodgkin lymphoma characterized by a proliferation of B cells whose nodular structure of follicular architecture is preserved. "A synergistic effect of fludarabine and rituximab have been shown in a follicular lymphoma B-cell line resistant to the cytotoxic activity of either drug alone, probably mediated through a down-modulation of membrane CD55." (PMID 17891600, 2007).
gall bladder cancer (1 paper, 2017). "CD55 overexpression has been found in breast and gall bladder cancer." (PMID 29283424, 2017).
gallbladder carcinoma (1 paper, 2015). "The expression levels of CD97 and CD55 in gallbladder carcinoma were associated with tumor severity." (PMID 25624904, 2015). "In addition, levels of CD97 and CD55 expression were independent predictors of shorter OS in patients with gallbladder carcinoma." (PMID 25624904, 2015).
gingivitis (1 paper, 2025). A disorder involving inflammation of the gums; may affect surrounding and supporting structures of the teeth. "The proteins CD55, GBP6, IGHV3-35, and IGKV1-6 are significant markers in the context of the host response to bacterial infections, particularly in relation to gingivitis and treatment outcomes." (PMID 41156831, 2025).
glioblastoma (1 paper, 2021). The most malignant astrocytic tumor (WHO grade IV). "However, lack of CD55 expression was found to be correlated with poor prognosis in solid tumors, such as breast cancer, and so further research is necessary to elucidate the effects of these proteins in glioblastoma at the organismal level." (PMID 34671342, 2021).
granulocytosis (1 paper, 2011). "In order to test whether increased C3a and C5a receptor signaling was involved in the displayed granulocytosis in Cd55-/- mice, we assessed circulating granulocyte numbers in Cd55-/-C3ar-/-C5ar-/- compound mice." (PMID 21984892, 2011). "The normal epinephrine response seen in mice lacking CD55 suggested that the displayed granulocytosis in these mice is not caused by a defect in margination of granulocytes." (PMID 21984892, 2011).
hemolysis (1 paper, 2023). Disruption of the integrity of the erythrocyte membrane causing release of hemoglobin. "The lack of the complement regulators CD55 and CD59 on PNH erythrocytes accounts for the hallmark of PNH, which is the chronic, complement‐mediated intravascular hemolysis." (PMID 36110036, 2023).
hypothyroidism (1 paper, 2011). Abnormally low levels of thyroid hormone. "Notably, expression pattern of four out of five genes affected by hypothyroidism (Angpt1, CD55, Cited1, and Mdk) was reversed by T3 treatment of hypothyroid animals, (p<0.05)." (PMID 21966411, 2011).
IgA nephropathy (1 paper, 2018). "Moreover, higher transcripts of CD46, CD55, CD59, and CFI were observed in recurrent IgAN nephropathy than in native kidney IgA nephropathy." (PMID 30356754, 2018).
IPEX syndrome (1 paper, 2025). "While present in almost all categories, their burden and distribution vary, with certain defects acting as clear ‘hotspots’, such as IPEX syndrome, APECED, LRBA, RAG1, RAG2, CD3γ, Helios, ARPC1B, and CD55 deficiencies." (PMID 41394846, 2025).
ischemic disease (1 paper, 2025). Lack of blood supply to an area of the body, resulting in impairment of tissue oxygenation. "CD55 promotes ischemic disease treatment, and its expression was higher in the APCS group than in the other groups." (PMID 40278796, 2025).
kidney tumors (1 paper, 2022). "Lin, CD11b, CD33, and CD44 were hypomethylated, while CD55 was hypermethylated in RMCs compared to the other kidney tumors." (PMID 36291828, 2022).
lactic acidosis (1 paper, 2008). Metabolic acidosis characterized by the accumulation of lactate in the body. "We further confirmed the induction of ERBB3, CD55, and PLAUR in response to lactic acidosis, and to the combination of hypoxia with lactic acidosis, via real-time PCR." (PMID 19057672, 2008). "Genes induced by lactic acidosis included: PLAUR, ERBB3, CD55, interleukin 15, CXCL16, angiogenin and MHC class I genes." (PMID 19057672, 2008).
laryngeal squamous cell carcinoma (1 paper, 2016). A squamous cell carcinoma that arises from the larynx. "In our tests, it was demonstrated that the expression of CD55 was elevated in cell lines of laryngeal squamous cell carcinoma after treatment with E. tirucalli latex, confirming its anti-inflammatory role." (PMID 27209356, 2016).
lung diseases (1 paper, 2024). "Through our research, we have come to understand that both the measured intensity and the distribution of the CD55 protein in the alveolar lining with maintained integrity must be considered to evaluate CD55 expression and its relation to lung diseases." (PMID 39337843, 2024). "A good understanding of the immunoregulatory complement protein CD55 expression in diseases could help in using CD55 as a biomarker for diagnosis as well as for treatment of lung diseases." (PMID 39337843, 2024).
lung squamous cell carcinoma (1 paper, 2018). "CD55 was highly expressed at the invading front of the tumor in lung squamous cell carcinoma." (PMID 29895866, 2018).
medullary thyroid carcinoma (1 paper, 2021). "Previous study has unveiled the role of CD55 to promote the adhesion of medullary thyroid carcinoma cells for rapid spread." (PMID 34805166, 2021).
meningioma (1 paper, 2018). A generally slow growing tumor attached to the dura mater. "While C1QA complement component has not been intensely studied in meningioma, different levels of complement regulatory membrane proteins, particularly CD55 and CD59, have been reported in meningioma by several groups." (PMID 29662628, 2018).
meningitis (1 paper, 2006). A disorder characterized by acute inflammation of the meninges of the brain and/or spinal cord. "First, the staining with anti-CD55 antibody was weak in the choroid plexus in control cases but was more prominent in one case of meningitis (Figure 3Ae/f,)." (PMID 16948860, 2006). "The regulation of CD55 expression by epithelial cells of the choroid plexus demonstrated minor changes between control and meningitis cases." (PMID 16948860, 2006). "In tissues, we found that CD55 was weakly expressed in control choroid plexus and ependyma but was abundantly expressed in meningitis." (PMID 16948860, 2006). "Ependymal cells express CD55, CD59 and CD46 antigens in normal cases and the stainings were increased in meningitis cases." (PMID 16948860, 2006). "In this study, we assessed the capacity of brain epithelial cells to express membrane-bound complement regulators (ie, CD35, CD46, CD55 and CD59) in vitro and in situ by immunostaining of control and meningitis human brain tissue sections." (PMID 16948860, 2006).
meningococcal meningitis (1 paper, 2021). "Additionally, levels of several complement regulators (CD35, CD46, CD55 and CD59) were shown in the CP of patients who suffered from meningococcal meningitis." (PMID 34425919, 2021).
mesothelioma (1 paper, 2010). A usually malignant and aggressive neoplasm of the mesothelium which is often associated with exposure to asbestos. "Our cell cultures were strongly positive for CD46, CD47, CD56 and CD63 and were also strongly positive for some markers never described before in mesothelioma cell lines, including CD55, CD90 and CD99." (PMID 20175889, 2010). "The four MM cell cultures were also strongly positive for some markers never described before in mesothelioma cell lines, including CD55, CD90 and CD99 that may represent new markers potentially useful for the isolation of cancer stem cells from MM." (PMID 20175889, 2010).
metastatic tumor (1 paper, 2016). "When we restricted the analysis to patients with metastatic tumor (stage 4), high mRNA levels of CD55 showed a trend for the association with overall and relapse-free survival but not in the subset of patients with localized tumors (stage 1–2–3)." (PMID 27043658, 2016).
muscular dystrophies (1 paper, 2024). "Reduced decay-accelerating factor (DAF)/CD55 mRNA levels were also reported for human dysferlinopathic muscles, although this was also observed in other muscular dystrophies." (PMID 39123261, 2024).
myasthenia (1 paper, 2019). "We previously interrogated CD55 (DAF) due to its critical role in muscle endplate damage in myasthenia and its relatively lower expression in the EOMs compared to limb muscle." (PMID 30696470, 2019).
myopia (1 paper, 2025). "In order to ascertain the significance of CD55 in the development of myopia caused by TGF-β2, siRNA CD55 was administered using AAV-DJ virus." (PMID 40862775, 2025). "The findings indicated that upregulation of CD55 could counteract the myopia-enhancing impact caused by TGF-β2." (PMID 40862775, 2025). "This study highlights the role of TGF-β2 in promoting myopia through the activation of complement components C3 and C5 and suppression of CD55, leading to enhanced inflammasome activity." (PMID 40862775, 2025). "Results showed that TGF-β2 exacerbated myopia by upregulating complement components C3 and C5, suppressing CD55, and activating inflammasome pathways through nuclear factor (NF)-κB signaling, leading to axial elongation and increased refractive errors." (PMID 40862775, 2025). "The results indicated the significance of CD55 in the development of myopia induced by TGF-β2." (PMID 40862775, 2025). "We conducted an experiment to determine if increasing the expression of CD55 in the eye could prevent the development of myopia induced by TGF-β2." (PMID 40862775, 2025). "The study suggests that gene therapy targeting CD55 could serve as a novel therapeutic strategy to mitigate myopia and related inflammatory processes, offering a promising avenue for managing this significant public health challenge." (PMID 40862775, 2025). "The overexpression of CD55 effectively counteracts these effects, suggesting that targeting the complement system, particularly CD55, could be a novel therapeutic strategy for myopia." (PMID 40862775, 2025).
ovarian tumour (1 paper, 2019). "Complement‐mediated cell killing of breast, lung and ovarian tumour cells by combined trastuzumab and pertuzumab was previously shown to be efficient only when all three CD46, CD55 and CD59 mCRPs were suppressed using the siRNA gene silencing technology." (PMID 31365168, 2019).
pancreatic adenocarcinoma (1 paper, 2018). "The increased levels of CD55 in pancreatic adenocarcinoma specimens suggest a protective role to prevent tumour cells from bystander killing by complement." (PMID 30404163, 2018).
Parasitemia (1 paper, 2021). "In P. falciparum growth assays, we observed a dose-dependent inhibition of parasite growth in the presence of anti-CD55 antibody relative to isotype control, with a ~ 40% reduction in relative parasitemia at the highest concentration of antibody (400 μg/ml)." (PMID 34028351, 2021). "(A) P. falciparum strain 3D7 parasitemia after 72 hr of growth in RBCS in the presence of increasing concentrations of anti-CD55 monoclonal antibodies, relative to isotype control antibody (BRIC 170) at the same concentration." (PMID 34028351, 2021). "In the presence of 400 μg/ml of anti-CD55 Fab fragments, we observed ~40% reduction in relative parasitemia, recapitulating the growth inhibitory activity observed with the bivalent anti-CD55 IgG antibody." (PMID 34028351, 2021). "(D) P. falciparum strain 3D7 parasitemia after 72 hr growth in 400 μg/ml Fab fragments generated from anti-CD55 polyclonal antibody or isogenic control." (PMID 34028351, 2021). "This was confirmed by immunofluorescence assays showing that P. falciparum invasion was restricted to the cells expressing CD55: the parasitemia in the minority, CD55-positive cells in the population was 22.5%, whereas less than 0.5% of the CD55-null cRBCs were infected." (PMID 34028351, 2021). "(B) Parasitemia of P. falciparum strain 3D7 after 72 hr growth in non-enzyme-treated RBCs with increasing concentrations of polyclonal anti-CD55 IgG antibody, relative to that in isotype control antibody at same concentration." (PMID 34028351, 2021). "(F) Parasitemia in population of CD55-CRISPR cRBCs, in which ~ 90% of the cells lack CD55 (CD55-negative), and the remaining are CD55-positive, as quantified by immunofluorescence assays." (PMID 34028351, 2021).